IL13 (interleukin 13)
Diseases named in the same sentence as IL13 in open-access papers (continued):
Sharing a sentence is not in itself a finding about the gene and the disease.
infection (continued). "In total, these studies demonstrate that IL-4/IL-13 polarization of macrophages generates a macrophage that is highly susceptible for EBOV entry and infection through enhancement of cell surface CLRs, and further highlight the importance of macrophages in the pathogenesis of EBOV." (PMID 31825972, 2019). "Even though IL-4 and IL-13 may have similar effects on immune cells, both cytokines are differentially regulated in mice during an infection with the rodent hookworm Nippostrongylus brasiliensis as well as in the present study." (PMID 31315623, 2019). "Pmacs exposed to IL-4/IL-13 were more susceptible to VLP fusion, demonstrating that enhanced entry, likely secondary to enhanced binding, is at least in part responsible for the increased infection observed in M2 macrophages." (PMID 31825972, 2019). "To verify that the effect observed in murine pmacs was not impacted by the lack of type 1 interferon signaling, we performed a similar experiment in WT pmacs and found that IL-4/IL-13 treatment increased infection 2.5-fold, consistent with the effect observed in Ifnar-/- cells." (PMID 31825972, 2019). "IL-13−/− and IL-4Rα−/− groups developed lesions similar to wild type upon initial infection." (PMID 30759882, 2019). "Compared with infections with low-uptake strains that secreted higher IL-17, infection with high-uptake C. neoformans strains induced higher secretions of bronchoalveolar lavage IL-4 and IL-13, the major cytokine profiles of type-2 immune responses." (PMID 30520685, 2019). "Interestingly, in contrast to the reduction in IL-4, IL-9 and IL-13 cytokine release later in infection, we saw a stronger, secondary peak of TGFβ at day 12 p.i.." (PMID 30998782, 2019). "Here, we performed time course kinetics experiments on bone marrow-derived macrophages (BMDMs) and human monocyte-derived macrophages (MDMs) alternatively activated with IL-4, IL-13, or a combination of IL-4/IL-13, followed by infection with Mtb clinical Beijing strain HN878." (PMID 30941122, 2019). "STAT6 phosphorylation, a marker of IL-13 pathway activation, also began to increase in HSCs, peaking at the same time point, and the production of collagen in HSCs was dramatically elevated at day 42 post-infection." (PMID 29554131, 2018). "Next, we found increased mRNA expression and activity levels of Arg1, mRNA expression of Fizz, Chi3l3, Cd209d, Cd209e, Mrc2 (Cd206), Marco, Il13, Saa1 (Serum amyloid A1 protein), Ccl17, Ccl19, Ccl20, Ccl22, and Ccl24 in Stat2−/− mice compared to WT mice during super-infection." (PMID 30337919, 2018). "IL-13 and IL-4 have emerged as key mediators of inflammation–and infection–driven fibrosis." (PMID 29782549, 2018). "Importantly, we show that miR-203-3p targets IL-33, an inducer of type 2 immunity, in HSCs to regulate the expansion and IL-13 production of hepatic ILC2s during infection." (PMID 29554131, 2018). "Because Arg-1 is only moderately expressed in T. cruzi-infected wildtype mice, we elucidated the role of Arg-1 and AAM during infection in IL-13-overexpressing (IL-13tg) mice, which are characterized by an inflammation-induced development of AAM and an accompanied elevated expression of Arg-1." (PMID 30555475, 2018). "The initial data on the adaptive immune response in different mouse strains infected with L. major have shown that the susceptibility or resistance to this infection is related to the production of certain cytokines of the Th1 or Th2 profile, respectively, IFN-γ, or IL-4 and IL-13." (PMID 30150896, 2018). "ES-polycys was divided into four sub-groups on the basis of hydrodynamic size, and the sub-groups that afforded the greatest protection following vaccination (sub-groups 3 and 4) also induced the greatest IL-13 (and IL-9) secretion by infection-primed MLN lymphocytes." (PMID 29540816, 2018).
infection (continued). "For example, delivery of antisense oligonucleotides targeting the IL-4Rα or a cell penetrating peptide targeting the STAT6 transcription factor (activated by both IL-4 and IL-13) to neonatal mice at the time of RSV infection reduces enhanced disease upon RSV re-infection of adults." (PMID 29915592, 2018). "Hence, our study confirms, that during infection IL-13 promotes a strong alternative macrophage activation." (PMID 30555475, 2018). "There were also significant main effects of location and infection upon IL-13 production in MLNs." (PMID 29518091, 2018). "IL-9R-deficient mice on both, BALB/c and C57BL/6 genetic background displayed (i) increased and prolonged parasite burden in the small intestine; (ii) reduced early degranulation of mucosal mast cells; (iii) reduced intestinal IL-13 expression and (iv) complete protection against a second infection." (PMID 29872093, 2018). "Therefore, IL-4/IL-13 responsive B cells are important for maintaining optimal cellular immunity during infection with S. mansoni." (PMID 30619289, 2018). "Furthermore, when CD4+ T cell type 2 responses were measured in the lungs at day 10 post-infection, Retnla +/- mice exhibited significantly increased numbers of IL-4+ and IL-13+ CD4+ T cells." (PMID 30500858, 2018). "Low levels of IL-13 may be required for homeostasis but IL-13 expression may be induced by infection or injury." (PMID 29438285, 2018). "Importantly, our data indicate that miR-203-3p targets IL-33, an inducer of type 2 immunity, in HSCs to regulate the expression of IL-13 in hepatic group 2 innate lymphoid cells (ILC2s) during infection." (PMID 29554131, 2018). "There was very little IL-13 and IL-9 produced by naïve lymphocytes in response to stimulation with these fractions, suggesting that these fractions contain parasite-specific antigens that drive Th2 cytokine release during acute infection." (PMID 29540816, 2018). "Interestingly, IL-13 showed an early induction in the acute phase of the viral infection and then decreased rapidly, to eventually increase after 60 days post-infection." (PMID 30416428, 2018). "Previous studies have demonstrated the production of interferon-gamma (IFN-γ), interleukin 12 (IL-12), nitric oxide (NO) and tumour necrosis factor alpha (TNF-α) in early stages of infection and later interleukin 13 (IL-13), interleukin 4 (IL-4) and interleukin 10 (IL-10)." (PMID 28655350, 2017). "Levels of nasosorption IL-13 against IL-5 (Z-score normalised) on day 0 were plotted as a 2D cluster, and demonstrate that there is reasonable discrimination between asthmatics (red dots) and healthy volunteers (blue dots) at baseline before infection." (PMID 28373098, 2017). "For example, IL-13 is a signature cytokine in the Th2 pathway, which is essential for granuloma formation, IgE production, basophilia, alternatively activated macrophage differentiation, and protection against fatal infection." (PMID 28969688, 2017). "Diminished IL-13 expression at this stage of infection correlated with diminished Muc5ac expression and a defect in worm clearance, while application of recombinant IL-13 or transfer of CD4+ T cells from infected WT mice was sufficient to restore worm clearance." (PMID 29045902, 2017). "Indeed Th2 responses were markedly decreased in cre+ mice and we observed reduced production of IL-9 and IL-13 in in vitro MLN restimulation cultures 35 days post infection." (PMID 28598427, 2017). "At the site of infection, Th2 cells secrete IL-13 upon exposure to IL-33." (PMID 29045902, 2017). "Gastro-intestinal helminth infections trigger the release of interleukin-33 (IL-33), which induces type-2 helper T cells (Th2 cells) at the site of infection to produce IL-13, thereby contributing to host resistance in a T cell receptor (TCR)-independent manner." (PMID 29045902, 2017).
infection (continued). "Importantly, stimulation of harvested MLN cells with 20μg/ml α-CD3 revealed that production of Th2 cytokines (IL-4, IL-5, IL-13 and IL- 10) peaked from day 6 to day 7 post-infection and diminished at day 9 and 12 post-infection." (PMID 28651009, 2017). "We hypothesized that ILC2s rather than T cells were the predominant source of the early IL-13 observed at day 4 after infection because this time point precedes the adaptive immune response during RSV infection." (PMID 27156176, 2016). "To determine whether IL-33 was required for activating ILC2s during RSV infection, we measured the total number of IL-13+ ILC2s in the lungs at day 4 after infection in WT and IL-33 KO mice." (PMID 27156176, 2016). "A lately increased cytokine IL-6, VEGF and IL-13 were at around 3 months after infection." (PMID 27830756, 2016). "Notably, RSV-infected TSLPR KO mice had significantly decreased levels of whole-lung IL-13 compared with RSV-infected WT mice at day 4 after infection." (PMID 27156176, 2016). "Infection with helminths has a profound effect on the immune system resulting in polarization towards Th2, characterized by high levels of cytokines such as interleukin-4 (IL-4), IL-5, IL-13 and high serum levels of immunoglobulin E." (PMID 26852392, 2016). "At day 4 after infection, we noted a significant increase in the total number of cells in the lung, the percentage of live cells that were ILCs and IL-13+ ILC2s, and the total number of ILCs and IL-13+ ILC2s in RSV-infected mice relative to mock-infected mice." (PMID 27156176, 2016). "Importantly, there was a statistically significant decrease in the number of IL-13+ ILC2s in the groups receiving TSLP neutralizing antibody at either 6 or 36 hours after infection compared with RSV-infected mice treated with isotype control antibody." (PMID 27156176, 2016). "In contrast, tuft cell hyperplasia induced by inoculation with exogenous IL-25 or due to epithelial restoration after cure of a primary infection enhanced tuft cell expansion and endogenous IL-25 production facilitating the development of protective Th2 responses with elevated levels of IL-13." (PMID 27658962, 2016). "However, IL-33 induced higher levels of IL-13 production in spleen and liver of mice with mixed infected than in male-only infection." (PMID 27445267, 2016). "Some studies in Cameroon found high levels of IL-13 associated with lower intensity of infection, but the present study did not establish such association." (PMID 27882241, 2016). "Moreover, there was a significant increase in the number of total ILCs and IL-13+ ILC2s that stained for Ki67, a marker of cellular proliferation, at day 4 after infection in the RSV-infected group compared with the mock-infected group." (PMID 27156176, 2016). "In this new model, primary infection of neonatal mice with rA2-19F induced a greater Th2 skewed response (higher frequency of Th2 cells, lower frequency of Th1 cells, and more IL13 expression) and further reductions in effector CD8+ T cell responses in the lungs compared to A2." (PMID 26231396, 2015). "The lack of correlation between IL13 exon 4 and IgA (r2 0.08, p = 0.31) may be due to the fact that the IL13 levels are transcripts at a single time point (12 weeks post-infection), but that serum IgA had accumulated over time." (PMID 26330386, 2015). "Therefore, we measured the expression of IL4Rα (receptor) on CD4+ T cells by flow cytometry and IL13 (ligand) expression in the lung by real-time PCR during primary infection." (PMID 26231396, 2015). "However, concurrent immune responses to an extremely diverse repertoire of antigens cause marked exacerbation of the fibrosis in an environment characterized by high levels of IL-13 and IL-4 in the chronic phase of infection." (PMID 25590646, 2015).
infection (continued). "In accordance with the elevated numbers of neutrophils and eosinophils in the peripheral blood and histological sections, we detected prominent increases in TH2 cytokines, such as IL-4, IL-5, IL-13 and IL-33, during the acute phase of infection, particularly from the 3rd day p.i. onward." (PMID 26135397, 2015). "The data so far would suggest that this is observed most robustly following a large dose of infection and in such a case may contribute significantly to worm removal via IL-13-controlled responses." (PMID 24942690, 2014). "This consequently elevated production of the Th2 cytokine, IL-4 and IL-13, may explain why these mice displayed reduced dendritic cell maturation and naïve T cells priming following infection." (PMID 24801628, 2014). "This showed that at all times after infection <1% of cells were positive for IFNγ or IL-13." (PMID 25474738, 2014). "However, unlike mangiferin, dexamethasone suppressed Th2 (IL-4, IL-5 and IL-13) responses as well as Th1 (IFN-γ and IL-12) responses, which is likely to increase patients' susceptibility on infection." (PMID 24955743, 2014). "Our initial data point to the Th cell compartment as the main cellular source of IL-4 and IL-13 early in the infection as revealed by analysis of IL-4 and IL-13 mRNA expression in the enriched pulmonary CD4+ population of WT mice (our own unpublished observation)." (PMID 24475277, 2014). "A careful analysis of the systemic (serum) cytokine levels in mice chronically infected with the Omani isolate revealed that type 1 (IFN-γ, TNF-α, GM-CSF), type 2 (IL-5, IL-13, to a lesser degree IL-4), and type 17 (IL-17) cytokines coexisted throughout the infection." (PMID 25398130, 2014). "At 63 days of infection, pulmonary gene expression of il13 was high in IL-13tg mice." (PMID 24979482, 2014). "However, at day 3 post-infection, the Socs4R108X/R108X mice showed significantly higher levels of cytokines and chemokines, such as IL-1β, IL-4, IL-5, IL-6, IL-12p40, IL-13, IFN-γ, and KC (CXCL1), MIP-2 (CXCL2) and MCP-1 (CCL2), respectively." (PMID 24809749, 2014). "Next, we investigated whether there were changes in the cytokine milieu at the site of infection using the thoracic cavity lavage and assessed the levels of several cytokines: IL-4, IL-5, IL-13, IL-25, IL-33, and IFNγ." (PMID 24663956, 2014). "There was a peak of cytokines IL-10, IL-13, IL-6 and IL-4, 17 weeks after infection." (PMID 24886277, 2014). "The IL-4, IL-5, IL-9, and IL-13 pretreatment responses were subtracted from 1 year posttreatment responses, and correlations between the changes and pretreatment infection intensity, a proxy of the amount of worm-derived antigen exposure upon treatment, were calculated." (PMID 24357629, 2014). "IL-1alpha, IL-2, IL-10 and IL-13 mRNA levels increased similarly during infection in all groups." (PMID 24204622, 2013). "LysMcreIL-4Rα-/lox mice which lack IL-4/IL-13 induced alternative activation of macrophages were found to have increased resistance to infection, while neutralization of endogenous arginase 1 with N-hydroxy-nor-L-arginine leads to complete healing in BALB/c mice." (PMID 24204259, 2013). "Impaired lamina propria Foxp3+ Treg-cell responses were associated with increased production of IL-4 and IL-13 by CD4+ T cells, demonstrating that ICOS dominantly downregulates Type 2 responses at the infection site, sharply contrasting with its Type 2-promoting effects within lymphoid tissue." (PMID 23319295, 2013). "ILC2 present in the lung of mice infected with influenza A virus (IAV) have been reported to produce abundant IL-13 during infection, which may contribute to airway hyperreactivity observed during experimental infection with respiratory viruses such as IAV." (PMID 24068930, 2013). "IL-4 and IL-13 induce a predictable pattern of gene expression in macrophages, regardless of the associated infection or disease." (PMID 23637937, 2013).
infection (continued). "Monitoring the sequential changes in the expression of cytokines following the infection showed that IL-33 expression peaked at day 6 PI, followed by the peak IL-4/IL-13 expression, suggesting that IL-33 plays a role in the initiation/amplification of the type 2-mediated immune response." (PMID 23536877, 2013). "Mice lacking either IL-4 or IL-13 are susceptible to infection with a high dose of T. muris which is expelled by wild-type animals." (PMID 23053395, 2012). "Two cytokines that play a major role in the resistance to infection are IL-4 and IL-13." (PMID 23053395, 2012). "Thus, filarial lymphedema with active infection is characterized by elevated plasma levels of IL-5, IL-13, and TGF-β." (PMID 22679524, 2012). "To test this hypothesis we depleted CD4+ T cells using a specific monoclonal antibody (mAb) prior to and after i.n. infection of WT and IL-13−/− mice." (PMID 21573182, 2011). "In this regard, it has been suggested that the production of an appropriate amount of IL-13 during infection could moderate the degree of pathogen-induced inflammation." (PMID 21931646, 2011). "In our study IL-13 was increased 5-fold in the lung as early as 24 hours after infection." (PMID 21573182, 2011). "αIL-13 mAb treatment depleted IL-13 protein levels 24 hours after infection." (PMID 21573182, 2011). "Consequently, it appears that healing and resolution of infection is dependent upon effector CD8 T cells; overall activation of CD8 T cells results in lower levels of IL-13 and IL-10 as well as IFNγ produced in response to infection." (PMID 21695103, 2011). "There is the potential that Chlamydia may induce innate and/or adaptive IL-13 responses to promote infection, which has significant implications for chlamydial respiratory and genital tract diseases, and associated conditions." (PMID 21573182, 2011). "Importantly the role of IL-13 in regulating infection was not limited to the lung as we showed that IL-13 also promoted susceptibility to Cmu genital tract infection." (PMID 21573182, 2011). "The capacity of IL-13 to modulate the innate immune response to infection in the present study may be underpinned by the development of macrophages with a reduced capacity to engulf and destroy Chlamydia in the lung." (PMID 21573182, 2011). "Interestingly, only half as many BALF macrophages from WT mice stained positive for Cmu 3 days after infection compared to those from IL-13−/− mice." (PMID 21573182, 2011). "Furthermore, several experimental models of fibrosis suggest that IL-13 is the dominant effector in toxin, infection, allergic, and posttransplant bronchiolitis obliterans models of fibrosis." (PMID 23283176, 2011). "We then characterised the influence of IL-13 on inflammatory responses to Cmu infection." (PMID 21573182, 2011). "An acute immune defense against infection was followed by a chronic inflammatory response, where activation of natural killer T cells and macrophages in the lung promoted persistent production of IL-13." (PMID 22205932, 2011). "However, we found that in both SHIV162p3 and SIVmac251 infected macaques, both Th-1 (IL-2, IFN-γ) and Th-2 (IL-4, IL-5, IL-6, IL-10, and IL-13) type cytokines were markedly elevated after infection." (PMID 21464951, 2011). "In studies of infection by Fasciola hepatica and S. mansoni, the secreted antioxidant, peroxiredoxin (Prx), was shown to induce Ym1-expressing AAMs, which enhanced the secretion of IL-4, IL-5 and IL-13 from naïve CD4+T cells." (PMID 21246055, 2011). "Although signaling via IL-4Rα plays a significant role in the outcome of infection with L. mexicana as well as L. major the cell targets for IL-4/IL-13 activity and whether they promote or inhibit the disease process differ significantly between species." (PMID 21245915, 2011). "Moreover, the depletion of IL-13 during infection of lung epithelial cells in vitro decreased the percentage of infected cells and reduced bacterial growth." (PMID 21573182, 2011).